ZEB1 (zinc finger E-box binding homeobox 1)
Diseases named in the same sentence as ZEB1 in open-access papers (continued):
Sharing a sentence is not in itself a finding about the gene and the disease.
tumor (continued). "Taken together, these data demonstrate that either the loss of E-Cadherin or the gain of ZEB1 induced alterations in SUM149 IBC tumor cells, suggesting that these genes directly regulate morphological alterations that have been associated with EMT." (PMID 23530113, 2013). "Our results show that EMT-associated factors such as ZEB1 and E-cadherin, as well as microRNAs that regulate these factors, change during tumor progression." (PMID 24376848, 2013). "We showed that positive expression of ZEB-1 was significantly associated with vascular invasion (p = 0.016), tumor TNM stage (p = 0.024), and prognosis (p = 0.025)." (PMID 24304617, 2013). "Immunofluorescence demonstrated an inverse relationship between ZEB1 and N-cadherin at the invasion front of control tumours, while membrane-associated expression of N-cadherin was retained up to the sharply defined borders of the shZEB1-derived tumour mass." (PMID 23818228, 2013). "In contrast, strong ZEB1 staining was seen to be associated with infiltrating stromal cells that had a mainly fibroblast appearance and accumulated in the tumor-host interface and along major vessels." (PMID 23153292, 2012). "The tumor-associated activated stroma seems to show a high ZEB1 expression in all carcinomas studied and can serve as a positive control." (PMID 24281177, 2010). "Importantly, ZEB1 expression was associated with aggressive tumor characteristics, including advanced tumor stage, undifferentiated-type histology, lymph node metastasis and vascular invasion." (PMID 41303618, 2025). "The opposing net effect in tumor growth may also be caused by a cell line-specific effect on tumor cells, immunological context and/or heterozygous zygotic Zeb1 loss, which may cloud ZEB1’s immunological functions in TAMs." (PMID 40595293, 2025). "Likewise, high ZEB1 or high CDH2 protein levels in the tumor cells (MART-1+) were associated with a worse prognosis." (PMID 41429767, 2025). "Notably, tumor cell proliferation was increased in KPC colonies upon ZEB1 loss in macrophages but remained unaffected in MC-38 ones." (PMID 40595293, 2025). "Thus, the environmentally induced, Zeb1-associated cancer cell plasticity as a driver of tumour progression also opens a therapeutic window." (PMID 39009641, 2024). "High expression of ZEB1 is associated with tumor aggressiveness of UM." (PMID 38191418, 2024). "Despite a prolonged exposure to the EMT stimulator TGF-β, ZEB1-deficient tumor cells maintained an epithelial phenotype, suggesting that ZEB1 may be required for the progress of EMT-related fibrosis." (PMID 38822380, 2024). "Hypoxia-induced ZEB1 activates the transcription of a large battery of genes encoding proteins that promote multiple steps in tumour progression, including tumour growth, stromal cell recruitment, extracellular matrix remodelling, and premetastatic niche formation." (PMID 38183060, 2024). "Interestingly, partial activation of EMT by the transcription factor ZEB1 was associated with tumor cell plasticity and metastasis formation in a PDAC mouse model." (PMID 38325381, 2024). "Consequently, ZEB1 inactivation in stromal fibroblasts suppressed tumor initiation, progression, and metastasis associated with reduced ECM remodeling, immune cell infiltration, and decreased angiogenesis." (PMID 37460910, 2023). "Among them, ZEB1 has been reported to be closely associated with tumor metastasis." (PMID 36805336, 2023). "High expression of CD151 supports tumor growth, and this dependency is associated with ZEB1/269." (PMID 35440541, 2022). "Unexpectedly, snail+ZEB1+CD44+ tumour cell density was associated with longer 5-year survival." (PMID 36358805, 2022). "Likewise, hypoxia-induced ZEB1 promotes CC progression via CCL8-dependent tumor-associated macrophage recruitment (Chen X.-J." (PMID 35769999, 2022). "Moreover, high levels of TGFB1/2 and ZEB1 were significantly associated with lymphatic invasion and advanced tumor stage." (PMID 34706749, 2021).
tumor (continued). "Additionally, the aberrant expression of ZEB1 has been found to be associated with tumor differentiation, lymph node metastasis, vascular invasion and EMT in CC." (PMID 34493213, 2021). "Zeb1 is a well-known EMT-TF associated with tumor progression." (PMID 32728068, 2020). "As IL-6 has also been shown to recruit mast cells to the tumor microenvironment, ZEB1-mediated IL-6 expression may explain the significant positive association we observed between ZEB1 expression and the abundance of intratumoral mast cells." (PMID 31780722, 2019). "ZEB1’s tumor promoting functions depend on a fine threshold of its expression and the deletion of one Zeb1 allele in either cancer cells or tumor-associated macrophages is sufficient to block tumor progression in Zeb1 (+/−) mice." (PMID 30910999, 2019). "ZEB1 expression was associated with a chemo-resistant tumor phenotype both in vitro and in vivo." (PMID 30976202, 2019). "A key player in this process is the zinc‐finger E‐box‐binding homeobox factor 1 (ZEB1), a transcription factor whose aberrant upregulation in tumor cells is directly linked to loss of E‐cadherin, reduced cellular adhesion, increased invasiveness, changes in cell polarity, and metastasis development." (PMID 28700115, 2017). "Tumor suppressive miRNAs mediate the degradation or post-transcriptional inhibition of transcripts encoding oncogenes and can target ZEB1/2, HMGB2, Bcl2 and HIF-1α, which contribute to the increased proliferation, invasion, and EMT and reduce the apoptosis of cancer cells." (PMID 28085956, 2017). "In addition, MicroRNA-200a has been reported to function as an EMT-associated tumor suppressor to upregulate E-cadherin by downregulating ZEB1/2, as the repressors of E-cadherin." (PMID 27580057, 2016). "Of the ten tumours with higher ZEB1, five (50%) had KRAS mutations." (PMID 27456471, 2016). "ZEB1 expression can be found in the epithelial cancer cells as well as the tumor-associated stroma." (PMID 24281177, 2010). "Furthermore, ZEB1 is associated with the regulation of genes governing cell motility and invasion, such as matrix metalloproteinases and integrins, which are critical factors in tumor invasion." (PMID 41481650, 2026). "EMT programs at the tumour-stroma boundary are induced by ZEB1 and lead to the transient loss of the basement membranes due to proteolytic cleavage of their components and down-regulated synthesis of laminin-5, a basement membrane component secreted by tumour cells." (PMID 37259089, 2023). "Interestingly, ZEB1 directly binds to and suppresses the expression of miR-141/-200c, suggesting that the loss of miR-141/-200c by ZEB1 expression results in a feed forward loop between TGFβ2 and ZEB1 that promotes tumor progression and recurrence." (PMID 33916548, 2021). "However, the feedback regulation between miR-200c and ZEB1 suggests that ZEB1 expression may be associated with tumor cell infiltration." (PMID 33396457, 2020). "Importantly, this study demonstrates that stroma-corrected ZEB1 transcriptional activity is associated with decreased abundance of tumor-infiltrating immune cells and decreased intratumoral inflammation, providing new insight into the role of ZEB1 as a suppressor of antitumor immune activity." (PMID 31780722, 2019). "Moreover, knockdown of lncRNA XIST significantly reduced the expression of ZEB1, which was the direct target of miR-200b-3p, and the tumor suppressive effects caused by knockdown of lncRNA XIST could be rescued by re-expression of ZEB1 in CRC cells." (PMID 28837144, 2017). "Interestingly, in other cases, ZEB1 was not only detected in the invasive front but also in the bulk of the tumor, suggesting that in addition to its role in promoting tumor invasion, it may also be implicated in tumor development." (PMID 27596438, 2016).
tumor (continued). "Hence, we asked whether ZEB1 expression in these tumours is associated with any particular subclass." (PMID 23818228, 2013). "Metastasis of solid tumors-the principal cause of cancer-related mortality-is often driven through activation of epithelial-mesenchymal transition (EMT), regulated by the transcription factor ZEB1, which is frequently upregulated during tumor progression." (PMID 42155637, 2026). "Mechanistically, ZFAS1 functions as a competitive endogenous RNA (ceRNA) that sequesters tumor-suppressive miRNAs including miR-150 and miR-193a-3p, thereby de-repressing downstream oncogenic targets such as ZEB1/MMP14 and RALY/HGF/c-Met." (PMID 41450817, 2026). "To validate the in vitro results, we generated separate A549 cell lines stably expressing ALKBH5, YAP, or ZEB1 to explore their functions in tumor growth and metastasis in vivo." (PMID 41216500, 2026). "In particular, SNAI1 can bind to the promoter regions of ZEB1 and activate its transcription, contributing to the downregulation of E-cadherin and promoting the EMT process, which is associated with tumor progression and metastasis." (PMID 41481650, 2026). "The expression levels of DEC1 and ZEB1 in tumor tissues and matched adjacent normal tissues of GC patients were detected by IHC." (PMID 40133270, 2025). "Studies have shown that mechanical signals, such as extracellular matrix stiffness and tension, can activate EMT-related transcription factors (e.g., SNAIL, TWIST, and ZEB1) to drive invasive tumor phenotypes." (PMID 40427044, 2025). "To gain insights into how ZEB1 in macrophages controls tumor and metastatic outgrowth, we utilized primary bone-marrow-derived macrophages (BMDMs) from LysMCtrl and LysMΔZeb1 mice." (PMID 40595293, 2025). "In a study, multi-omic analysis showed that the expression of zinc finger E-box-binding homeobox 1 (ZEB1) is indicative of an intermediate state that tumor cells go through during the progression of neuroendocrine prostate cancer (NEPC)." (PMID 40584966, 2025). "Subsequent experimental data, however, demonstrate that the OCRA Tabletop MRI System successfully detected ZEB1 activation correlated with modified liquid properties within tumor tissue microenvironments." (PMID 40856386, 2025). "We found that genes involved in EMT—CDH1, CDH5, and ZEB1—allowed for the differentiation of healthy cells from tumor samples." (PMID 40332096, 2025). "MiR-200 family members are well-known tumor suppressors that are involved in the inhibition of epithelial–mesenchymal transition (EMT)-mediated tumor invasion by targeting ZEB1/2." (PMID 40002172, 2025). "We determined that the percentage of GZMA+CD8+ T cells was remarkably increased, especially in the core region of tumor tissues, with ZEB1 KD." (PMID 40924501, 2025). "ZEB1 directs tumor cells toward glycolysis for energy production by controlling the transcription of numerous important glycolytic enzymes." (PMID 40584966, 2025). "Taken together, the results indicate that targeting ZEB1 in tumor cells effectively inhibited recruitment and polarization of neutrophils, leading to activation of CD8+ T cells and a synergistic antitumor effect with chemoimmunotherapy in PC." (PMID 40924501, 2025). "In other cancers, lactylation regulates EMT transcription factors such as ZEB1(Zinc finger E-box-binding homeobox 1), endowing tumor cells with migratory and invasive potential." (PMID 41583433, 2025). "Macrophage-specific genetic ablation of the EMT inducer ZEB1 reveals its pivotal role in intracellular cytokine trafficking, boosting cytotoxic T cell abundance and immune responses, thereby reducing tumor growth and metastatic colonization in mice." (PMID 40595293, 2025). "It plays an important role in the pathogenesis of several tumor types by targeting ZEB1 and ZEB2, which are transcriptional repressors of E-cadherin, thereby maintaining epithelial integrity." (PMID 41226545, 2025).
tumor (continued). "Together, the ZEB1-regulated EMT signaling contributes to establishing a pro-metastatic hyaluronan network in the tumor microenvironment, presenting a novel strategy to target this network and suppress lung cancer progression and metastasis." (PMID 40005870, 2025). "This will allow the design of rational combination treatments targeting ZEB1 to convert naturally resistant PDAC CAFs to a reovirus-susceptible stroma, which will allow concurrent targeting of both tumor cells and CAFs." (PMID 41244268, 2025). "Consistently, a recent study showed that deletion of endothelial ZEB1 in tumor-bearing mice reduced tumor angiogenesis and led to sustained normalization of tumor vasculature by epigenetically repressing TGF-β signaling." (PMID 40160462, 2025). "The tumor microenvironment via secretion of TGF-β inducing ZEB1 expression drives an EMT transition, critical for the conversion of non-CSC to CSC and the maintenance of the CSC-like state." (PMID 40361430, 2025). "Tumor volume and weight were reduced in nude mice injected with A549 cells following sh-circ-ZEB1 transfection." (PMID 39802932, 2025). "LOXL2 regulates ECM remodeling and stiffness, a key factor in tumor invasion and metastasis, often via ZEB1-mediated upregulation." (PMID 41164190, 2025). "Collectively, our study identified a new tumor-suppressive function of ZEB1 in macrophages, exposing an important immunological context provided by ZEB1 in TAMs." (PMID 40595293, 2025). "When Beclin-1 is knocked out, tumor cells acquire EMT mesenchymal characteristics by stabilizing the mRNA level of ZEB1." (PMID 40229278, 2025). "Accumulated TGF-β in the tumor microenvironment (TME) stimulates the SMAD-Snail-ZEB1 axis, while the Wnt-β-catenin-ZEB1 cascade is also ongoing." (PMID 40358200, 2025). "In light of the ID8-centered aggravation of carcinomatosis by ZEB1 in TAMs29, its requirement for efficient anti-tumor immunity in gastrointestinal cancer models uncovered by us shows that relevant immuno-oncological contextures are manifested by ZEB1 in TAMs." (PMID 40595293, 2025). "Meanwhile, ZEB1 blockade attenuates CD44+ neutrophil–induced CD8+ T cell exhaustion by reducing tumor-derived SPP1 secretion, which otherwise promotes exhaustion through activation of the PD-L1/PD-1 pathway." (PMID 40924501, 2025). "Single-cell and spatial transcriptomics revealed that ZEB1 ablation promoted tumor pyroptosis by recruiting and activating GZMA+CD8+ T cells in the tumor core through epigenetic upregulation of CXCL16." (PMID 40924501, 2025). "NF-κB also regulates epithelial-mesenchymal transition (EMT) via transcriptional activation of Snail, Twist, and ZEB1, thus accelerating tumor invasion and dissemination." (PMID 40999361, 2025). "The reduction in ZEB1 disrupts the cancer cell-macrophage positive feedback loop, decreasing inflammation and oxidative stress, and ultimately preventing tumor progression." (PMID 41148802, 2025). "ZEB1 deficiency prevents P.g.-induced vimentin and MMP-9 upregulation, reducing tumor cell migration, indicating its crucial role in EMT." (PMID 40924302, 2025). "Subsequent intercellular communication analysis revealed that compared with the other 3 subtypes of CD8+ T cells, GZMA+CD8+ T cells had the strongest interaction with tumor cells upon ZEB1 inhibition." (PMID 40924501, 2025). "ET-1 enhances YAP/ZEB1 nuclear interaction, forming a transcriptional complex with AP-1 to sustain tumor progression." (PMID 40630468, 2025). "For example, the mammosphere formation ability of M13HS tumor hybrids was significantly decreased after both Snail-KO and Zeb1-KO, highlighting the requirement of both EMT transcription factors for mammosphere formation." (PMID 40806166, 2025). "ZEB1 expression was heightened in younger patients, and dynamin-related protein 1 (Drp1) protein abundance was elevated in a subgroup of tumor tissue compared to healthy tissue." (PMID 40830586, 2025).
tumor (continued). "Noteworthily, ZEB1 modulates tumor metastasis through its influence on tumor cell motility and dissemination." (PMID 40771411, 2025). "When combined with gemcitabine, EGCG suppressed tumor migration and invasion by downregulating the zinc finger E-box binding homeobox 1 (ZEB1), β-Catenin, and vimentin pathways, while inhibiting Akt and EMT pathways." (PMID 40918466, 2025). "Inhibition of ZEB1 notably enhanced the tumor-suppressive effect of gemcitabine and prolonged overall survival (OS) in immunocompetent mice." (PMID 40924501, 2025). "lncRNA n384546/TUG1 elevated in PTC, these lncRNAs adsorb miR-145-5p to upregulate AKT3 and ZEB1, synergistically enhancing tumor invasiveness." (PMID 40530008, 2025). "MTMR2 inhibits the signaling cascade, suppressing IRF-1 expression, relieving the inhibitory effects of IRF-1 on ZEB1, and facilitating epithelial-mesenchymal transition in tumor cells." (PMID 40909948, 2025). "Mechanistically, HULC induces EMT via the miR-200a-3p/ZEB1 signaling pathway, thereby facilitating tumor progression and metastasis." (PMID 40909946, 2025). "We identified 6 genes and finally focused on ZEB1, which has been reported to promote tumor progression and migration." (PMID 40924501, 2025). "ZEB1 in macrophages appears largely dispensable for organogenesis and hematopoiesis, but modulates the anti-tumor immune response." (PMID 40595293, 2025). "Our findings demonstrated that PPI effectively downregulated the expression of ZEB1, Snail, Slug, and Twist at both the RNA and protein levels, thereby highlighting its inhibitory impact on tumor EMT." (PMID 40429774, 2025). "Tumor cells with high ZEB1 expression exhibit heightened dependence on GPX4, as GPX4 counteracts the oxidative effects of intracellular peroxides on PUFAs in cellular membranes, thereby attenuating ferroptosis." (PMID 40709182, 2025). "Probing ZEB1 protein abundance in tumor cells-free liver and patient-matching tumor tissue, we observed its relevance as a tumor marker in 25% of patients only." (PMID 40830586, 2025). "Further experiments confirmed that ZEB1 KD in combination with gemcitabine and anti–PD-1 therapy resulted in superior tumor suppression." (PMID 40924501, 2025). "The results showed that ZEB1 inhibition induced more dramatic tumor regression in immunocompetent mice." (PMID 40924501, 2025). "In conclusion, this study identified a ZEB1-driven reprogramming of the tumor microenvironment that contributed to resistance to both immunotherapy and chemotherapy in PC." (PMID 40924501, 2025). "The study concluded that E-cadherin and zinc finger E-box-binding homeobox 1 are key predictors of lymph node metastasis, tumor grade, and stage in PTC." (PMID 40787244, 2025). "The spatial transcriptomics and mIHC analyses indicated that there were fewer neutrophils infiltrated within the tumor’s core region when ZEB1 was knocked down, aligning with our scRNA-Seq findings." (PMID 40924501, 2025). "Tumor-promoting CAF subsets, including inflammatory CAFs (iCAFs) and Zeb1-positive CAFs, play critical roles in facilitating tumor growth and metastasis." (PMID 40784879, 2025). "In tumor progression, hypoxia stimulates the expression of the ZEB1 gene, which increases the motility of tumor cells and stimulates the growth of new blood vessels." (PMID 41226394, 2025). "Mechanistically, E-cadherin restoration suppresses metastatic dissemination through transcriptional repression of N-cadherin via ZEB1/2-mediated pathways, while ZO-1 and occludin reinforce intercellular tight junctions to impede tumor cell intravasation." (PMID 40136409, 2025). "In HBV-related HCC, metformin has been shown to inhibit tumor cell proliferation by negatively regulating the HULC/p18/miR-200a/ZEB1 signaling pathway." (PMID 40909946, 2025).